AR (androgen receptor)
Diseases named in the same sentence as AR in open-access papers (continued):
Sharing a sentence is not in itself a finding about the gene and the disease.
glioblastoma (continued). "We have previously shown that inhibiting AR signaling led to glioblastoma cell death, suggesting that AR is essential for the cellular survival of glioblastoma." (PMID 34681618, 2021). "Pharmacological inhibition of AR and AR genetic silencing in glioblastoma cell lines induced cell death, while AR antagonists significantly decreased human glioblastomas implanted subcutaneously." (PMID 34681618, 2021). "More than two decades ago, Brentani and cols detected AR’s expression in 42% of 12 glioblastoma samples." (PMID 33752729, 2021). "Herein, ALZ003 targeting AR for degradation strongly exhibits the therapeutic effect on glioblastoma, including TMZ-resistant tumor, in vitro and in vivo." (PMID 31896509, 2020). "Accordingly, AR expression was significantly increased in glioblastoma compared with normal brain tissue, and high AR expression significantly correlated with shorter survival period." (PMID 31896509, 2020). "The current study further emphasizes the promoting role of AR in growth and proliferation of glioblastoma, and indicates the disruption of AR functions by ALZ003 is potential to prevent DHEA-induced drug resistance." (PMID 31896509, 2020). "Based on our study, AR is a promising target in glioblastoma, driving us to study effect the inhibitor targeting AR, including BBB-penetrating enzalutamide." (PMID 31896509, 2020). "We conclude that the strategy targeting AR will be potential for treating glioblastoma, and ALZ003 will benefit patients’ life in the future." (PMID 31896509, 2020). "Particularly, we found that ALZ003 induces FBXL2-mediated AR ubiquitination, leading to downregulation of AR in glioblastoma." (PMID 31896509, 2020). "In consistence with bioinformatics analysis, AR expression was obviously increased in human glioblastoma specimens determined by western blotting analysis." (PMID 31896509, 2020). "To understand the clinical relevance of AR in glioblastoma, we analyzed the correlation between AR expression and prognosis using Oncomine and SurvExpress." (PMID 31896509, 2020). "ALZ003, a structurally analog to curcumin with superior stability, bioavailability, and potency, exhibits stronger anti-tumor effect on glioblastoma in vitro and in vivo through decreasing AR expression." (PMID 31896509, 2020). "Based on the previous study showing that curcumin analogs, ALZ003 (also called ASC-JM17) and ASC-J9 are potent enhancer for AR protein degradation, we postulated that ALZ003 is potential for treating glioblastoma through the decrease of AR protein expression." (PMID 31896509, 2020). "Of interest, it was reported before that high expression levels of AR in glioblastoma translates into sensitivity to the AR antagonist enzalutamide." (PMID 31747973, 2019). "Quantitative-PCR (qPCR) showed that AR-RNA was overexpressed (2.76-315,984 fold) in 93% of 30 glioblastoma samples of both men and women patients." (PMID 29731997, 2018). "We have observed that androgen receptor (AR) is amplified in glioblastomas at the DNA, RNA and protein levels." (PMID 29731997, 2018). "The AR-RNA expression findings were validated in 703 glioblastomas by analysis of several datasets, including the TCGA." (PMID 29731997, 2018). "Following these findings, we examined the effect of pharmacological inhibition of androgen receptor in vitro and in vivo, as well as of genetic silencing of the receptor in glioblastoma cell lines." (PMID 29731997, 2018). "AR antagonists, induced concentration-dependent death in three glioblastoma cell lines, as well as in two glioma initiating cell lines." (PMID 29731997, 2018). "The AR gene was amplified in 27% of glioblastoma specimens from men (n=22) and of 38.2% from women (n=21)." (PMID 29731997, 2018). "The in vivo experiment described here shows that the AR antagonist enzalutamide efficiently reduces the growth of human glioblastoma." (PMID 29731997, 2018).
glioblastoma (continued). "Western blot analysis revealed AR protein induction (2-106-fold) in 56% of the glioblastomas samples (n=16) of both men and women patients, and in the three GBM cell lines tested (2B)." (PMID 29731997, 2018). "AR-RNA was overexpressed (>2.5 fold) in 93% (n=30), and AR-protein was induced (>two fold) in 56% of the glioblastomas samples (n=16)." (PMID 29731997, 2018). "AR antagonists enzalutamide and bicalutamide can not only promote cell death in glioblastoma, but enzalutamide can also alleviate glioblastoma volume and proliferation, thereby inhibiting glioblastoma progression." (PMID 39256355, 2024). "Therefore, to determine AR activity in glioblastoma samples, the expression of specific ARGs was determined to calculate the so-called AR score." (PMID 38233838, 2024). "The androgen receptor (AR) has been demonstrated to play a role in the pathogenesis of glioblastoma; however, the implications of circulating testosterone levels in the biology of glioblastoma remain unknown." (PMID 38233838, 2024). "In any case, increasing the number of patients and measuring their AR activity will confirm whether the AR score is a good prognostic factor for glioblastoma." (PMID 38233838, 2024). "The identification of a possible association between the androgenic status and the prognosis in glioblastoma could facilitate the use of the AR as a plausible therapeutic target." (PMID 38233838, 2024). "Interestingly, in case of glioblastoma a link between AR and MAPK signaling with regard to therapy resistance has recently been described." (PMID 36906590, 2023). "As a more novel approach to exploiting EGFR activity in glioblastoma therapy, future research endeavours could focus on targeting the androgen receptor (AR) in combination with anti-EGFR treatments." (PMID 37857607, 2023). "Therefore, we followed this unmet need, explored a new therapeutic target for this disease, and found that the androgen receptor (AR) is amplified at the DNA and RNA levels, and 56% of glioblastomas over-express AR protein." (PMID 38203506, 2023). "The most interesting target with the strongest expression dynamics across the cell line panel as identified by this approach was the androgen receptor (AR) which has recently been reported to play an important role in prognosis and therapy resistance of glioblastoma." (PMID 36906590, 2023). "Thus, the roles of the AR in tumorigenesis of glioblastomas have attracted a lot of research in wide-ranging investigations." (PMID 36235203, 2022). "Hsp27 also has an established client relationship with Androgen Receptor (AR) that is excessively expressed in the glioblastoma, which might explain the sex disparities in glioblastoma patients." (PMID 36358853, 2022). "Additionally, in AR+ glioblastoma cell lines and xenograft models, inhibition of AR with enzalutamide or seviteronel has been shown to provide sensitisation to radiation therapy." (PMID 35618789, 2022). "The AR-signaling axis-involved regulation of cell proliferation and colony formation in human glioblastoma cells may contribute to tumorigenesis and subsequent malignance of human GBM." (PMID 36013056, 2022). "In various types of human glioblastoma cell lines, testosterone and 5α-dihydrotestosterone could promote cell proliferation, migration, and invasion, but flutamide, an antagonist of AR, blocked such an induction." (PMID 36235203, 2022). "We studied whether combining EGFR kinase inhibitors with AR antagonists would induce synergistic efficacy in glioblastoma." (PMID 34681618, 2021). "Based on this and the significant role of EGFR in glioblastoma, we explored whether AR activation in glioblastoma is achieved through EGFR signaling." (PMID 34681618, 2021).
glioblastoma (continued). "However, to establish an association between T and the prevalence of glioblastomas in men, AR and T levels in a larger group of biopsies from male and female glioblastoma patients must be measured." (PMID 33752729, 2021). "AR is amplified at DNA and RNA levels; 56% of glioblastomas express AR protein." (PMID 34681618, 2021). "AR is overexpressed in most glioblastomas and is a potential therapeutic target." (PMID 34681618, 2021). "Our results demonstrate that EGFR (HER1) signaling affects AR activation in glioblastoma." (PMID 34681618, 2021). "EGFR signaling is involved in AR activation in glioblastoma." (PMID 34681618, 2021). "As AR expression is positively correlated with glioblastoma malignancy, we attempted to determine whether inhibition of AR is effective to kill glioblastoma." (PMID 31896509, 2020). "However, in the presence of GPX4 knockdown, AR failed to induce the resistance to ALZ003, suggesting that ALZ003 inhibits glioblastoma through suppressing AR-mediated GPX4 expression." (PMID 31896509, 2020). "Taken together, AR potentiates TMZ resistance for glioblastoma, and ALZ003-mediated AR ubiquitination might open a new insight into therapeutic strategy for TMZ resistant glioblastoma." (PMID 31896509, 2020). "Importantly, FBXL2 knockdown significantly attenuated ALZ003-induced cytotoxicity, further suggesting that ALZ003 suppresses the growth of glioblastoma through inducing FBXL2-mediated AR ubiquitination." (PMID 31896509, 2020). "In addition, we also found that AR expression was further increased in TMZ-resistant glioblastoma cells, A172-R, U87MG-R and Pt#3-R, all of which were established in the previous studies." (PMID 31896509, 2020). "Therefore, a drug targeting AR for direct degradation is potential to be developed for treating glioblastoma." (PMID 31896509, 2020). "Based on these investigation, we hypothesize that AR promotes glioblastoma growth and induces drug resistance." (PMID 31896509, 2020). "Herein, we attempt to understand whether AR regulates the survival of glioblastoma, and to clarify whether a potential compound targeting AR is effective to treat glioblastoma." (PMID 31896509, 2020). "We hypothesize that, in DHEA-enriched microenvironment, glioblastoma is more resistant in response to TMZ treatment through ligand-induced AR activation." (PMID 31896509, 2020). "Thirty percent of the glioblastomas (n=21) also expressed a constitutively active AR-splice-variant (AR-V7/AR3) lacking the Ligand-Binding-Domain." (PMID 29731997, 2018). "Silencing of AR expression by siRNA induced cell death in the three tested glioblastoma cell lines." (PMID 29731997, 2018). "The documented upregulation of the androgen receptor in glioblastoma might therefore contribute to TRPM8 overexpression in the brain tumor." (PMID 29221175, 2017). "Androgen receptor (AR) contributes to the progression of glioblastoma (GBM), which is consistent with the sex difference in GBM, which has a higher incidence in males than in females." (PMID 42130715, 2026). "Therefore, AR activity plays a role in the biology of glioblastoma." (PMID 38233838, 2024). "However, the involvement of AR in glioblastoma and the potential androgen receptor-regulated signaling pathways in glioblastoma were largely unknown." (PMID 38203506, 2023). "Interestingly, AR expression has been found in CSCs from different types of tumors, such as breast, ovarian, and glioblastoma, demonstrating its potential to positively regulate the expression of genes associated with stemness, as well as the proliferation and self-renewal." (PMID 37894767, 2023). "Besides, silencing the AR using RNA interference induced the death of human glioblastoma cells." (PMID 36235203, 2022). "Therefore, the testosterone AR signaling axis may contribute to tumorigenesis and malignance of glioblastomas." (PMID 36013056, 2022).
glioblastoma (continued). "We sought to analyse the androgen receptor (AR) in glioblastoma (GBM) due to the location of the AR gene on chromosome X, often reported with shorter survival and higher prevalence of GBM among males." (PMID 35661403, 2022). "AR blockade can significantly downregulate c-Myc protein levels in GBM cells both in vitro and in vivo with known cellular functions of c-Myc in cell proliferation and glycolysis in glioblastomas." (PMID 34094902, 2021). "However, in glioblastoma development which relies on the production of neurosteroids, the role of AR still remains unclear." (PMID 31896509, 2020). "However, in DHEA-enriched microenvironment, the role of AR in acquiring resistance of glioblastoma remains unknown." (PMID 31896509, 2020). "However, whether a strategy targeting AR is effective for glioblastoma is unclear because of the difficulty in developing a drug with BBB-crossing ability." (PMID 31896509, 2020). "Conversely, the Androgen receptor pathway, known to regulate the growth of glioblastoma multiforme (GBM) in men39 is exclusively and preferentially altered in this cancer type." (PMID 29713020, 2018). "For instance, curcumin analogs promote androgen receptor (AR) ubiquitination, disrupting GPX4-mediated redox homeostasis and inhibiting temozolomide-resistant glioblastoma growth." (PMID 39935430, 2025). "In glioblastoma cells, the derivative ALZ003 reduces GPX4 expression by promoting FBXL2-mediated ubiquitination of the androgen receptor (AR), resulting in significant lipid peroxidation and ROS accumulation." (PMID 41515171, 2025). "As a result, the combination of AR antagonists and EGFR kinase inhibitors was expected to be a more effective glioblastoma therapeutic method." (PMID 39256355, 2024). "Considering that dexamethasone is commonly used in patients with glioblastoma to control symptoms related to brain edema, the activation of the AR pathway via heterodimerization with GR may lead to an increase in the expression of ARGs and, consequently, an increase in the AR score." (PMID 38233838, 2024). "For example, AR genes were mainly highly expressed in tumors like Pancreatic Cancer (PAAD), Glioblastoma (GBM) and Thymoma (THYM)." (PMID 36479101, 2022). "Compared to normal human HA-h astrocytes, expressions of AR mRNA in human TMZ-sensitive U87 MG and TMZ-resistant U87 MG-R glioblastoma cells were elevated by 95% and 79%, respectively." (PMID 36235203, 2022). "Our in vitro results showed that suppressing the AR activation concurrently alleviated the testosterone-induced PARD3B mRNA expression, cell proliferation, and colony formation in human glioblastoma cells." (PMID 36013056, 2022). "Our present results further revealed that levels of AR mRNA in TMZ-sensitive U87 MG and TMZ-resistant U87 MG-R glioblastoma cells were significantly higher than in normal human astrocytes." (PMID 36235203, 2022). "The AR signaling pathway contributes to enzalutamide-induced insults to human TMZ-sensitive and -resistant glioblastoma cells." (PMID 36235203, 2022). "The cell viability of three glioblastoma cell lines (U87MG, A172, T98G) was studied at 72 h following treatment with EGFR kinase inhibitors combined with enzalutamide (AR antagonist) or as monotherapy." (PMID 34681618, 2021). "Werner and cols determined that AR expression at the transcript and protein levels in LN18, T98G glioblastoma cell lines, patient-derived xenografts (PDX), and human tumors overlapped with the expression of this receptor in primary prostate cancer." (PMID 33752729, 2021). "Targeting androgen receptor (AR) has been shown to be promising in treating glioblastoma (GBM) in cell culture and flank implant models but the mechanisms remain unclear." (PMID 34094902, 2021). "Our findings suggest that EGFR signaling is involved in AR activation in glioblastoma and buttresses the concept of combining an EGFR signaling inhibitor with AR antagonists as a potential glioblastoma treatment." (PMID 34681618, 2021).
glioblastoma (continued). "AR, androgen receptor; ER, estrogen receptor; GBM, glioblastoma multiforme; NSC, non‐small‐cell." (PMID 29577611, 2018). "A previous study indicated that androgen can activate MAOA expression by AR-regulated Sp1 binding to MAOA promoter in human neuroblastoma and glioblastoma cells." (PMID 29066975, 2017). "Interestingly, a cross-talk between the AR and epidermal growth factor receptor (EGFR) pathways has been described in glioblastoma cells and AR activation in vitro regulates transcription programs related to radiation-induced DNA damage repair." (PMID 38233838, 2024). "In addition, expressions of AR mRNA and protein in human TMZ-sensitive U87 MG and -resistant U87 MG-R glioblastoma cells were elevated compared to normal human astrocytes." (PMID 36235203, 2022). "Fascinatingly, suppressing AR activity with enzalutamide, a specific inhibitor of the AR, concurrently attenuated testosterone-induced enhancements of cell proliferation and colony formation in human U87 MG and GBM5401 glioblastoma cells." (PMID 36013056, 2022). "Suppressing AR activity concurrently resulted in significant attenuations of testosterone-induced PARD3B gene expression, cell proliferation, and colony formation in human glioblastoma cells." (PMID 36013056, 2022). "Androgen receptor ubiquitination induced by the curcumin analog was demonstrated to suppress GPX4, thereby inducing ferroptosis and reversing temozolomide resistance in glioblastoma." (PMID 35151318, 2022). "In addition, expressions of AR mRNA and protein in human TMZ-sensitive U87 MG and -resistant U987 MG-R glioblastoma cells were upregulated compared to normal human astrocytes." (PMID 36235203, 2022). "There are also no data on the difference in AR levels between men and women in glioblastomas, but in animal models and humans, the content of AR is higher in a variety of male brain areas compared with the female brain." (PMID 33752729, 2021). "Considering its major role in glioblastoma, we explored whether EGFR is involved in AR signaling in this tumor." (PMID 34681618, 2021). "Since AKT is a known secondary messenger that plays a role downstream of EGFR signaling in glioblastoma, we explored whether AKT is involved in EGFR-induced AR regulation." (PMID 34681618, 2021). "In addition to inhibiting the growth of glioblastoma, ALZ003 significantly extended the survival period of transplanted mice, and significantly decreased AR expression in the tumor area." (PMID 31896509, 2020). "Tumor suppressor activities of IGSF8 have been previously addressed in PCa, although with respect to cell motility rather than AR signaling, and in glioblastomas." (PMID 26036626, 2015). "However, the implications of circulating testosterone levels in AR activity in glioblastoma have not been analyzed yet." (PMID 38233838, 2024). "The efficacy of AR antagonists, demonstrated in our mouse models, may not universally apply to all glioblastoma cases." (PMID 38203506, 2023). "Importantly, we previously confirmed that DHEA, the ligand of AR, promotes acquiring resistance of glioblastoma in response to TMZ, further driving us to elucidate whether AR is a promising target to overcome drug resistance." (PMID 31896509, 2020).